MIR548AG2 (microRNA 548ag-2)
Synonyms: hsa-mir-548ag-2
Gene: MicroRNA gene on chromosome 20 (60,564,562 to 60,564,625, forward strand). Ensembl gene ENSG00000265617.
Homologues: Orthologues: chimpanzee MIR548AG2 (100% identical). Paralogues in human: MIR548Z (83% identical), MIR548H3 (81% identical), MIR548O2 (81% identical), MIR548AG1 (80% identical), MIR548AN (80% identical), MIR548AX (80% identical), MIR548AA1 (78% identical), MIR548AY (77% identical), MIR548AH (75% identical), MIR548AJ1 (75% identical), MIR548X2 (75% identical), MIR548AZ (73% identical), and 13 more.